PPARG (peroxisome proliferator activated receptor gamma)
Diseases named in the same sentence as PPARG in open-access papers (continued):
Sharing a sentence is not in itself a finding about the gene and the disease.
melanoma (continued). "Following intravenous injection of B16 melanoma cells, increased lung metastases were observed in mice with myeloid-specific PPARγ knockout, further reinforcing the role of MDSCs’ PPARγ in metastasis." (PMID 33946986, 2021). "Pro-tumorigenic paracrine action of the PPARγ agonist rosiglitazone (RGZ) in melanoma has been reported, however, showing that PPARγ activation results in complex and context-dependent outcomes, the molecular bases of which remain poorly characterized." (PMID 33846376, 2021). "To confirm the involvement of PPARγ in melanoma growth inhibition following ASAH1 loss, we simultaneously knocked down PPARγ and ASAH1 in melanoma cells." (PMID 33766731, 2021). "Here we identify the Thioredoxin-interacting protein (TXNIP) as a gene, which expression is regulated by PPARγ in melanoma cells." (PMID 33846376, 2021). "With this approach, we found that TXNIP expression was downregulated by PPARγ activation in A375 metastatic melanoma cells (absolute fold change −1.36; False discovery rate 0.031;7)." (PMID 33846376, 2021). "In human melanoma, the activation of PPARγ remodels the expression and localization of surface integrins, particularly integrin β-3 and integrin α-5, to increase cellular adhesiveness and distal metastatic seeding." (PMID 33946986, 2021). "KL expression in melanoma cells is enhanced by PPARγ, and KL or PPARγ agonist rosiglitazone treatment reduce melanoma growth in mice." (PMID 33520985, 2020). "Further research in in vivo models of melanoma is needed to better understand of interaction between PPARγ and TLR4 signaling in this cancer." (PMID 32665906, 2020). "Consistently, treatment with PPARγ agonists dramatically blocks the proliferation of melanoma cells." (PMID 31138783, 2019). "A similar anti-proliferative effect of PPARγ activation on melanoma-derived CAFs has also been reported using the PPARγ agonist 15d-PGJ2." (PMID 30925918, 2019). "Collectively, our findings demonstrate that CLQ has a great potential in the treatment of melanoma through activation of PPARγ." (PMID 31138783, 2019). "Considering the chemoresistance of current FDA-approved treatments of malignant melanoma, specific targeting of PPARγ is suggested to be a critical therapeutic approach." (PMID 31089369, 2019). "High PPARγ expression in melanoma cells is a favorable prognostic factor for progression-free survival." (PMID 30424016, 2018). "Some data show that PPARγ induces differentiation in response to natural or pharmacological agonists, reproducing some of the effects promoted by αMSH in melanocytes and melanoma cells." (PMID 28835664, 2017). "Due to its key role in the control of cell proliferation, PPARγ agonists are used in therapeutic models for different forms of cancer, including melanoma." (PMID 29020973, 2017). "We previously identified a new pathway between αMSH and Peroxisome Proliferator Activated Receptor (PPARγ) on B16-F10 mouse melanoma cell line." (PMID 29020973, 2017). "In conclusion, our data indicated that FAK inhibited the expression of E-cadherin via p-SrcY416/p-ERK1/2/ p-Stat3Y705 and PPARγ/miR-125b/Stat3 signaling pathway in both melanoma cells and human tumors." (PMID 28108732, 2017). "We previously identified the αMSH/Peroxisome Proliferator Activated Receptor (PPARγ) pathway as a new pathway on the B16-F10 mouse melanoma cell line." (PMID 29020973, 2017). "Both the COX-2 and the PPARγ were found in melanoma by immunohistological staining and activation of PPARγ by rosiglitazone attenuated COX-2 expression." (PMID 25250328, 2014). "T. Boon for providing the human melanoma cell lines and Dr. S. Chavanas for the dominant negative mutant and the inhibitor of PPARg." (PMID 23493799, 2013). "PPARγ is a transcription factor that is overexpressed in several types of cancer, particularly melanomas." (PMID 23493799, 2013).
melanoma (continued). "Here we present a comprehensive study assessing the anti-tumorigenic effects of a panel of PPARα and PPARγ agonists on a variety of melanoma cell lines." (PMID 23049949, 2012). "Additional support for a therapeutic role for PPARγ comes from tissue microarray analyses of normal and tumor tissue from patients with malignant melanoma described by Meyer and colleagues." (PMID 20614003, 2010). "In this special issue of PPAR research, the first section contains two research articles that focus on the role of PPARγ in malignant melanoma." (PMID 20614003, 2010). "Nuclear hormone receptors, including RXR and PPARγ, represent novel therapeutic targets in melanoma." (PMID 19859558, 2010). "They report that PPARγ and cyclooxygenase 2 (Cox2) are stage-dependent prognostic markers of malignant melanoma." (PMID 20614003, 2010). "A mechanistic study described by Klopper and colleagues illustrates how the response of poorly differentiated melanoma cells to PPARγ and retinoid X receptor agonists is mediated through the calcium binding protein S100A2." (PMID 20614003, 2010). "In this report, we have demonstrated for the first time that the combination of a rexinoid and TZD effectively inhibits growth of differentiated melanoma expressing PPARγ and RXRγ using an in vivo model." (PMID 19267912, 2009). "Only a few studies have focussed on PPARγ expression and effects of PPARγ agonists in melanoma cell lines (summarized inTable 1)." (PMID 18483619, 2008). "Several PPARγ agonists inhibit the proliferation of human malignant melanomas, and the PPARα agonist fenofibrate has antimetastatic effects on melanoma tumors in vivo in a hamster model." (PMID 19125181, 2008). "In the current review, we discuss the role ofPPARs, in particular PPARγ in melanoma and their potential role as a molecular target for melanoma therapy." (PMID 18483619, 2008). "If this inactivation of the PI3K/Akt pathway by rosiglitazone also contributes to the antiproliferative effect of PPARγ agonists in melanoma needs to be further elucidated." (PMID 18483619, 2008). "As several studies have shown an antiproliferative effect of PPARγagonists on several tumour entities including melanoma, this review focuses onthe role of the PPARγ as a possible target in melanoma therapy." (PMID 18483619, 2008). "The use of PPARγ agonists in melanoma therapy has to becarefully weighted against considerable,undesirable side effects, as their mode of action is not fullyunderstood and even pro-proliferative effects havebeen described." (PMID 18483619, 2008). "Many reports have indicated the central role of PPARγ in the control of malignant cell growth invarious tumour entities including melanoma." (PMID 18483619, 2008). "In other cancer cells, resistance pathways which areconstitutively activated in melanoma cells were affected throughPPARγ agonist independent from PPARγ activation." (PMID 18483619, 2008). "Additionally, PPARα agonist fenofibrate and PPARγ agonist pioglitazone have been shown to enhance the antitumor activity of cytotoxic T lymphocytes and invariant natural killer T cells in melanoma, respectively." (PMID 39735727, 2024). "The role of PPARγ in melanoma metastasis is unclear; however, it might be suggested that the role of this receptor depends on the target: melanoma cell or tumor microenvironment." (PMID 36834531, 2023). "Notably, the protein levels of PPARα and PPARγ were higher in mouse and human melanoma cells than in normal melanocytes." (PMID 36834531, 2023). "We therefore determined whether agonist anti-CD40 mAb (FGK45.5 or FGK) in combination with PPARγ (T0070907 or T007) or PPARδ (GSK3787 or GSK) inhibitor may achieve efficient antitumor responses in mice with established B16 melanoma (left)." (PMID 37291146, 2023). "However, several studies reported the direct involvement of PPARγ in apoptosis, including in melanoma cells." (PMID 36834531, 2023).
melanoma (continued). "Although previous studies indicated only the involvement of PPARγ in the regulation of cell cycle proteins in melanoma, studies conducted on other types of cancer confirmed that all PPAR isoforms might have a similar biological effect." (PMID 36834531, 2023). "Importantly, PPARγ seems to play an important role not only in the regulation of the proliferation of melanoma cells but there is also the direct link to the tumor-stroma interactions." (PMID 36834531, 2023). "Various PPARγ agonists exert antiproliferative activity towards melanoma in vitro and in vivo." (PMID 36834531, 2023). "The majority of studies are focused on PPARγ activity towards melanoma cells." (PMID 36834531, 2023). "Liliane Michaliks’ group further showed that the PPARγ agonist rosiglitazone activates a tumorigenic secretion program of cytokines, chemokines, and pro-angiogenic factors in melanoma cells, leading to a tumor progression- and metastasis-favoring microenvironment." (PMID 35954274, 2022). "In addition, several studies have described beneficial roles of PPARγ agonists in melanoma cells through inhibition of proliferation, or activation of apoptosis and/or differentiation." (PMID 33846376, 2021). "Here we reveal that PPARγ activation reduces the expression of TXNIP in human melanoma cells." (PMID 33846376, 2021). "We thus sought to assess what contribution could TXNIP make to the roles played by PPARγ and its agonists in melanoma cells." (PMID 33846376, 2021). "Unfortunately, poor knowledge exists on this matter as the only evidence for a role of lipid signaling in melanoma biology comes from two recent papers in which the authors independently remarked an anti-tumor effect of PPARβ/δ and PPARγ in melanoma progression and metastasis." (PMID 31998652, 2019). "A further TMA (n = 194) consisted of MM metastases from 36 patients with metastatic stage IV melanoma who had participated in a randomized phase II trial using a stroma-directed biomodulatory approach combining COX-2/ PPARγ-targeting with metronomic low-dose chemotherapy." (PMID 30424016, 2018). "Moreover, in the same study, preliminary experiments showed that mouse melanoma cells responded to αMSH by reducing proliferation and that PPARγ was involved in this effect." (PMID 29020973, 2017). "The expression of PPARγ protein may therefore serve as a positive prognostic marker indicating the responsiveness to stroma-targeted therapy in the metastatic stage (IV) of melanoma." (PMID 23049949, 2012). "There is increasing evidence that the peroxisome proliferator-activated receptor-γ (PPARγ)-binding ligands, may be effective for the treatment of melanoma and other tumors." (PMID 23049949, 2012). "There is a larger body of research evaluating the role of PPARγ activation in melanoma." (PMID 19267912, 2009). "Likewise, PPARG immunoreactivity significantly increased from benign nevi (0%) to malignant melanomas (22%) and melanoma metastases (33%; P < .001)." (PMID 19639032, 2009). "Besides PPARG immunoreactivity, stage of the primary melanoma was also a significant prognostic factor for progression-free survival (P = .016)." (PMID 19639032, 2009). "In addition, evidence has been accumulated that PPARγ isexpressed in human melanoma cells and that PPARγ specific agonists dose-dependently inhibitedproliferation of melanoma cells." (PMID 18483619, 2008). "The PPARγ agonists rosiglitazone, troglitazone,pioglitazone, and ciglitazone showed an increase in cell proliferation of allsix melanoma cell lines tested in low concentrations (3 μM), however, in higherconcentrations (>30 μM) a significant growth-inhibitory effect wasobserverd." (PMID 18483619, 2008). "Interestingly, all four PPARγ agonists showed an increase in cellproliferation of all six melanoma cell lines at concentrations of 3 μM." (PMID 18483619, 2008).
melanoma (continued). "However, in melanoma, activation of PPARγ enhances the expression of surface integrins, specifically integrin β-3 and integrin α-5, increasing the capacity for distant metastasis and implantation of cancer cells, a process also associated with the inhibition of thioredoxin-interacting protein." (PMID 37251321, 2023). "Since this kinase positively correlated with PPARγ activity, and as its genetic and pharmacologic inhibition together with PD1-blocking Ab improved metabolic fitness and anti-tumor activity of T-cells against murine melanoma, PPARγ antagonists may be envisioned as agents to improve tumor control." (PMID 37686465, 2023). "However, PPARγ might be a promising approach for targetspecific anticancer strategy in the treatment of melanoma." (PMID 18483619, 2008). "Research has shown that the peroxisome proliferator-activated receptor gamma (PPAR-γ) and its ligands exhibit protective effects against melanoma." (PMID 40214488, 2025). "Agonists of PPARγ, including ciglitazone, troglitazone, rosiglitazone, pioglitazone and 15d-PGJ2 inhibited proliferation of melanoma cell lines representing different stages of cancer progression." (PMID 36834531, 2023). "In contrast to the anti-tumorigenic function of PPARγ in DCs proposed by many studies, Zhao and colleagues identified a paracrine Wnt5a-β-catenin-PPAR-γ signaling pathway driving FAO in DCs by which melanomas escape from immunotherapies." (PMID 35954274, 2022). "Simultaneous knockdown of PPARγ and ASAH1 inhibited the ability of C2 ceramide or rosiglitazone to activate PPAR-responsive firefly-luciferase reporter activity in melanoma cells." (PMID 33766731, 2021). "As revealed by the data set of Riker melanoma, the expressions of FAK, ERK1/2 are up-regulated while the expressions of PPARγ, C21orf34 and E-cadherin are down-regulated in metastatic melanoma, as compared with normal controls." (PMID 28108732, 2017). "Accordingly, the inhibition of PPARγ by GW9662 reverted the effects on cell cycle modulators (p27, p21, Cyclin D1 and cyclin E) promoted by αMSH in both melanoma cell lines." (PMID 29020973, 2017). "As indicated by the data set of Talantov melanoma, compared with normal controls, the expressions of FAK, Src, ERK1/2 and Stat3 are up-regulated, while the expression of PPARγ is down-regulated in metastatic melanoma." (PMID 28108732, 2017). "In differentiation-supported conditions, TAFH RNAi-treated melanoma cells started to express chondrogenic-specific SOX9, NKX3.2 and RUNX2; adipogenic PPARG; and neurogenic NTRK2, NF-M and SYP mRNAs at 48 h post-stimulation of differentiation." (PMID 27499390, 2016). "These compounds are selective antagonists of the CB1, TRPV1, PPARα, PPARγ and GPR55 receptors respectively, the mRNA of which were found in B16 melanoma cells." (PMID 22429826, 2012). "The PPARγ agonists ciglitazone, troglitazone and 15d-PGJ2 and the PPARα ligand WY-14643 were tested on four melanoma cell lines (A375, M24met, 1205Lu and MelJuso) to generalize our findings." (PMID 23049949, 2012). "In summary, we have identified potential downstream mediators of rexinoid and TZD treatment in a poorly differentiated melanoma and found that alterations in S100A2 expression affect RXR and PPARγ signaling in A375(DRO) cells." (PMID 19859558, 2010). "In this report, we have examined global gene expression in a poorly differentiated cancer model, the amelanotic melanoma cell line A375(DRO), after treatment with PPARγ and RXR ligands." (PMID 19859558, 2010). "PPARG agonists were shown to downregulate COX2, potentiate the apoptotic effects of chemotherapeutic agents, and inhibit the growth of human melanoma cell lines in vitro." (PMID 19639032, 2009).
melanoma (continued). "Placha and colleagues performed in vitro proliferation analyses on two PPARγ expressing melanoma cells: WM35, a primary melanoma lesion and A375." (PMID 19267912, 2009). "Our own results showedexpression of PPARγ in six different human melanoma cells MV3, Lox, MeWo, G361, FemX-1, and UISO-Mel6,which were established from primary malignant melanoma or metastatic melanomalymph node." (PMID 18483619, 2008). "Additionally, the beneficiary effect of PPARγ antagonist was also confirmed in in vivo studies, where MM902 inhibited tumor growth in the mouse xenograft model of melanoma." (PMID 36834531, 2023). "Although some studies exist on PPARα in melanoma, PPARγ has, to our knowledge, never been investigated in relation to TILs and survival in any form of cancer." (PMID 36230483, 2022). "Moreover, MYC (log FC = −3.32), PPARG (log FC = 2.17), ZIC2 (log FC = 3.62) were also dysregulated in melanoma." (PMID 31681565, 2019). "The PLC/PPARγ axis, inside the MC1R transduction machinery, could represent an element which potentially offers new therapeutic approaches for melanoma." (PMID 29020973, 2017). "The respective roles of signaling pathways involving PPARγ and SAPK/JNK in melanoma development and in MICA expression are still unknown and should be analyzed in further studies." (PMID 23493799, 2013). "The PPARγ specific agonists 15-deoxy-Δ12,14 prostaglandin J2 (15d-PGJ2), troglitazone, and rosiglitazone inhibited cell proliferation in four melanoma cell lines dose-dependently, whereas a specific agonist of peroxisome proliferator-activated receptor alpha (WY-14643) did not exert this effect." (PMID 23049949, 2012). "Clinicopathologic variables of melanoma patients were correlated with COX2 and PPARG expression." (PMID 19639032, 2009). "Interestingly, combined treatment with the PPARγ agonist pioglitazone, the COX2 inhibitor rofecoxib, and angiostatic chemotherapy stabilized or even reversed chemorefractory melanoma progression, though in only 11% of the treated patients." (PMID 19125181, 2008). "Analysis of the published data showed that the inhibition of PPARγ decreased the mRNA level of ENO1 in BLCA cells, while Rosiglitazone (a PPARγ agonist) could increase the transcription level of ENO1 in melanoma cells." (PMID 37024456, 2023). "Similarly, treatment of melanoma cells expressing non-specific shRNA with rosiglitazone, a PPARγ agonist, also increased PPAR-responsive firefly-luciferase reporter activity compared with vehicle-treated cells expressing non-specific shRNA." (PMID 33766731, 2021). "In contrast the IC50 of the PPARγ agonists ciglitazone and troglitazone could not be reached with the highest dose of 100 μM tested on A375, M24met and MelJuso melanoma cell lines." (PMID 23049949, 2012). "Further experiments, treating melanoma cell lines with αMSH in the presence/absence of GW9662, as an inhibitor of PPARγ, confirmed the key role of this transcription factor in decreasing cell proliferation in response to the hormone exposure." (PMID 29020973, 2017).